PPP1R13B (protein phosphatase 1 regulatory subunit 13B)
Synonyms: ASPP1; KIAA0771; p53BP2-like; p85
Tractability: Small molecule: a structure with a bound ligand is known. Antibody: its Gene Ontology location is reachable by antibodies, with high confidence. PROTAC: ubiquitination databases record sites on it; its protein half-life has been measured.
Gene: Protein-coding gene on chromosome 14 (103,733,195 to 103,847,614, reverse strand). Ensembl gene ENSG00000088808.
Subcellular location: Cytoplasm; Nucleus
Subcellular location (Human Protein Atlas): Nucleoplasm; Cytosol
Pathways (Reactome):
Programmed Cell Death: Activation of PUMA and translocation to mitochondria
Gene Ontology:
Molecular function: protein binding
Biological process: negative regulation of cell cycle; apoptotic process; regulation of apoptotic process
Cellular component: cytoplasm; cytosol; nucleoplasm; nucleus
Genetic constraint (gnomAD): Loss-of-function variants: 43 observed, 119.07 expected, observed/expected ratio (o/e) 0.36, 90% interval 0.28 to 0.47. The upper end of that interval is the gene's LOEUF score, 0.47, which puts it in group 2 of 6, group 1 being the genes least tolerant of losing a copy. Missense variants: 1,221 observed, 1,442.3 expected, observed/expected ratio (o/e) 0.85, 90% interval 0.81 to 0.89. Synonymous variants: 541 observed, 570.89 expected, observed/expected ratio (o/e) 0.95, 90% interval 0.88 to 1.02.
Homologues: Orthologues: chimpanzee PPP1R13B (99% identical), macaque PPP1R13B (98% identical), dog PPP1R13B (92% identical), mouse Ppp1r13b (92% identical), rat Ppp1r13b (92% identical), guinea pig PPP1R13B (91% identical), rabbit PPP1R13B (89% identical), pig PPP1R13B (87% identical), tropical clawed frog ppp1r13b (73% identical), zebrafish ppp1r13bb (66% identical), zebrafish ppp1r13ba (61% identical), Drosophila melanogaster ASPP (28% identical), and 1 more. Paralogues in human: TP53BP2 (49% identical).
Diseases named in the same sentence as PPP1R13B in open-access papers:
PPP1R13B is named in the same sentence as 37 diseases in open-access papers, as found by Europe PMC text mining. Sharing a sentence is not in itself a finding about the gene and the disease. The quoted sentences say what the papers report.
leukemia (5 papers, 2007 to 2024). A malignant (clonal) hematologic disorder, involving hematopoietic stem cells and characterized by the presence of primitive or atypical myeloid or lymphoid cells in the bone marrow and the blood. "Interestingly, this analysis revealed that PPP1R13B mRNA is frequently decreased in AML – with the lowest mean PPP1R13B mRNA levels preferentially detected in higher risk leukemia." (PMID 38195541, 2024). "In addition, this screen also allowed comparison of healthy myeloid tissue with leukemia blasts specimens, which unveiled attenuated PPP1R13B mRNA levels in the AML cohort." (PMID 38195541, 2024). "To evaluate the significance of attenuated PPP1R13B mRNA expression patterns in leukemia, we next performed a database RNAseq screen on a large pan-cancer data platform, which revealed specifically low PPP1R13B expression levels in AML when compared to twenty-two other tumor entities." (PMID 38195541, 2024). "PPP1R13B mRNA expression patterns thereby define a distinct prognostic profile - which is not reflected by the European leukemia net (ELN) risk score." (PMID 38195541, 2024).
acute lymphoblastic leukemia (2 papers, 2024). Leukemia with an acute onset, characterized by the presence of lymphoblasts in the bone marrow and the peripheral blood. "Further, attenuated expression levels of ASPP1 have been described in patients suffering from acute lymphoblastic leukemia (ALL) – which again was linked to methylation of the PPP1R13B promoter region." (PMID 38195541, 2024).
pulmonary fibrosis (2 papers, 2022 to 2024). Chronic progressive interstitial lung disorder characterized by the replacement of the lung tissue by connective tissue, leading to progressive dyspnea, respiratory failure, or right heart failure. "Moreover, it was inconsistent with the previous study, which results suggested that PPP1R13B regulated by circ‐012091 promoted the proliferation and migration of lung fibroblasts through regulation of ERS and autophagy and played a crucial role in the development of pulmonary fibrosis in silicosis." (PMID 35783909, 2022).
depression (1 paper, 2019). "Whereas previous studies observed decreased activation of adenylate cyclase and PKA in depression, in this study, we found a significant decrease of PPP1R13B and PPP2R2B, two phosphate family proteins that counterbalance the action of PKA, in the hippocampus." (PMID 30983951, 2019).
glaucoma (1 paper, 2020). Increased pressure in the eyeball due to obstruction of the outflow of aqueous humor. "It is important to note that some of our positional candidates—Eif5, Bag5, Klc1, and Ppp1r13b—have been previously demonstrated to play a role in glaucoma and/or RGC health." (PMID 32174956, 2020).
insomnia (1 paper, 2025). A sleep disorder characterized by difficulty in falling asleep and/or remaining asleep. "Finally, SNPs in the genetic region of chromosome 14 near genes PPP1R13B, ZFYVE21 and LINC00637 have been previously associated with smoking, risk taking, problematic alcohol use, number of sexual partners, sex hormone-binding levels, BIP, SZC and insomnia." (PMID 39975919, 2025).
myeloid leukemia (1 paper, 2024). A clonal proliferation of myeloid cells and their precursors in the bone marrow, peripheral blood, and spleen. "We now reveal in a lentiviral PPP1R13B knock-down AML model, that deregulation of ASPP1 directly influences proliferation rates of myeloid leukemia cells, arguing for a contribution to the biology and aggressiveness of myeloid malignancies as well." (PMID 38195541, 2024).
tumor (23 papers, 2007 to 2024). "A total of 127 genes were upregulated upon JQ1 treatment and included those with a role in translational repression (EIF4EBP2, PAIP2B), induction of apoptosis (PPP1R13B) and tumour suppression (glucocorticosteroid (GC)-responsive gene FKBP51)." (PMID 23872705, 2013). "Our study has provided the first glimpse of the genetic underpinnings of AciCC, highlighting changes in the tumor suppressors CDKN2A and PPP1R13B." (PMID 23653877, 2013). "We next assessed PPP1R13B levels in a large pan-cancer RNAseq data platform, which includes 56,938 unique samples from three well-defined datasets (TCGA/TARGET/GTEx), and confirm specifically low PPP1R13B expression levels in AML when compared to 22 other tumor entities." (PMID 38195541, 2024).
cancer (11 papers, 2007 to 2025). A tumor composed of atypical neoplastic, often pleomorphic cells that invade other tissues. "Of 94 germline familial variants identified with predicted functional impact, 37 SNPs/indels were detected in 28 genes, 2 of which (MLH1 and PRH1-TAS2R14) have known association with CRC and 4 others (PPP1R13B, LAMA5, FTO, and NLRP14) have known association with non-CRC cancers." (PMID 37627102, 2023).
PPP1R13B also shares sentences with these, for which no sentence is quoted: colorectal cancer (4 papers); acute myeloid leukemia (3); breast carcinoma (3); hepatocellular carcinoma (2); lung carcinoma (2); lymphoma (2); acute leukemia (1); astrocytoma (1); breast tumours (1); cervical carcinoma (1); choriocarcinoma (1); chronic lymphocytic leukemia (1); chronic lymphoid leukemia (1); clear-cell renal cell carcinoma (1); colorectal adenocarcinoma (1); diffuse large B-cell lymphoma (1); gastric cancer (1); head and neck squamous cell carcinoma (1); hematological malignancy (1); lymph node metastasis (1); lymphoid neoplasm (1); melanoma (1); metastasis (1); Multiple Myeloma (1); Myelodysplasia (1); neuroblastoma (1); pancreatic cancer (1); silicosis (1).